SPDYE17 (speedy/RINGO cell cycle regulator family member E17)
Tractability: No criterion of Open Targets' tractability assessment is met for any kind of drug.
Gene: Protein-coding gene on chromosome 7 (77,022,306 to 77,032,361, reverse strand). Ensembl gene ENSG00000186645.
Gene Ontology:
Molecular function: protein kinase binding
Homologues: Orthologues: rat Spdye4 (49% identical), mouse Spdye4a (48% identical), mouse Spdye4b (44% identical). Paralogues in human: SPDYE10 (100% identical), SPDYE11 (100% identical), SPDYE8 (100% identical), SPDYE9 (100% identical), SPDYE13 (99% identical), SPDYE14 (99% identical), SPDYE15 (99% identical), SPDYE12 (99% identical), SPDYE3 (89% identical), SPDYE18 (83% identical), SPDYE16 (83% identical), SPDYE2 (83% identical), and 6 more.